ATM (ATM serine/threonine kinase)
Diseases named in the same sentence as ATM in open-access papers (continued):
Sharing a sentence is not in itself a finding about the gene and the disease.
tumor (continued). "A clinical study indicated that other key mediators of DDR, such as CHK1, ATM, CHK2, and ATR, may also contribute to ICI combinations in several tumor types, and the efficacy of other DDR inhibitors combined with ICI in the treatment of ovarian cancer requires further validation." (PMID 34712221, 2021). "Archival formalin-fixed tumor specimens were available for targeted NGS from 57 of 70 patients (for the remaining 13 patients there was either inadequate tissue or test failure) and for ATM IHC testing from 60 patients (for the remaining 10 patients there was inadequate tissue)." (PMID 34552099, 2021). "Notably, targeting components of Pol I using the selective inhibitor CX5461 to treat tumors with MYC amplification has shown the selective killing of tumor cells through the activation of non-canonical ATM signaling." (PMID 34359683, 2021). "Furthermore, novel non-canonical roles of DNA repair factors such as ATM in tumor growth and treatment are also emerging." (PMID 32566127, 2020). "Therefore, targeting key enzymes involved in DNA DSB repair, particularly the protein kinases ATM, ATR and DNA-Pkcs, in relatively radioresistant HPV-negative HNSCC that are DSB repair-proficient is considered to be an approach to sensitise these tumours to radiotherapy." (PMID 32517381, 2020). "Furthermore, blocking the ATM-dependent DNA damage response pathway during NK cell activation led to enhanced NK cell activity, downregulation of KLRG1, improved persistence, and better tumor clearance in a murine B cell lymphoma model." (PMID 33120910, 2020). "In some hypoxic tumor cells, the expression of homologous recombination repair (HRR) pathway-related genes, such as RAD51 and BCRA1, will be downregulated, while the expression of non-homologous end-joining (NHEJ) pathway-related genes, such as ATM and DNA-PKcs, will be upregulated." (PMID 32974200, 2020). "Molecular studies further determined that enforced miR-184 plays tumor-suppressive roles in RB cells and enhances chemosensitivity via enhancing G2/M phase arrest and cellular apoptosis mediated through directly targeting SLC7A5 and its downstream ATR/ATM pathway." (PMID 31803607, 2019). "Indeed, ATM-associated tumours do not show the HRD signature characterised by large-scale state transitions, suggesting that tumorigenesis in BRCA1 variant carriers and ATM variant carriers occurs by different mechanisms." (PMID 29665859, 2018). "The in vivo assay showed that compared with other treatments, PDMP was most effective in inhibiting tumor growth, prolonging survival time, decreasing expression of CD31, CD133, and ALDH1, inducing G1 phase arrest, increasing the apoptosis rate, and in expressing ATM and γ-H2AX." (PMID 29416613, 2018). "ATM exists in two different cellular pools: (i) nuclear ATM, involved in DNA repair and (ii) cytoplasmic ATM, which acts as a ROS sensor and an activator of the tuberous sclerosis complex 2 (TSC2) tumour suppressor by signalling to LKB1 and AMPK to relieve mTORC1 repression of autophagy." (PMID 29682156, 2018).
tumor (continued). "Knockout of ATM expression and inhibition of ATM function in GBM cell lines inhibited cell proliferation and migration, increased sensitivity to apoptosis induced by therapeutic agents in vitro, and markedly suppressed GBM tumor growth and promoted animal survival." (PMID 29348882, 2017). "ATM expression was not prognostic in ES-HPBC in a multivariable analysis, however, because ATM protein expression level is strongly associated with known clinico-pathological prognostic factors such as tumor size, grade and LN status in ES-HPBC." (PMID 27741524, 2016). "Tumor histology (HE staining) was similar in the three experimental groups, all the tumors being densely cellular and highly undifferentiated, independent of ATM silencing." (PMID 26053094, 2015). "MYCN expression was undetectable in GI-ME-Nkd-3650, GI-ME-Nkd-1463 and GI-ME-Nkd-LacZ cells by Western Blotting and real-time quantitative PCR, thus further corroborating the conclusion that the tumor promoting effect of ATM silencing in the NB cell background does not require MYCN." (PMID 26053094, 2015). "The present data demonstrate that exposure of either normal, mitogenically activated lymphocytes, or tumor cell lines (A549, TK6) to metformin leads to a decrease in the level of constitutive phosphorylation of H2AX on Ser139 and constitutive activation of ATM." (PMID 22067284, 2011). "Collectively, tumor size 1 and 2 showed hypermethylation of DR5 (68%; P = 0.002), DCR1 (63%; P = 0.001) and DCR2 (80%; P = 0.0000001) as well as hypomethylation of DR4 (58%; P = 0.011), FLIP (61%; P = 0.007) and ATM (59%; P = 0.013) after Benjamini Hochberg correction." (PMID 21092294, 2010). "Additionally, proteins involved in the regulation of the cell cycle (e.g., ATM and STAT3), cell proliferation (e.g., LYN and SRRT), metabolism (e.g., GOT2, PPP1CA, and PYGB), and the regulation of Ca2+ flux (e.g., ANXA6 and CALM1) were also found phosphorylated in the tumor cells." (PMID 40129242, 2025). "Moreover, ATM-3507 does not impair muscle structure and function, suggesting that ATM-3507 may target the cytoskeleton of tumor cells but not muscle tissues." (PMID 37686101, 2023). "Patients with ATM expression but without kinase activity showed phenotypes like classical A-T in which ATM is completely absent, with a minor improvement in survival and malignancy latency until their thirties; after that period no survival or tumor free patients were reported." (PMID 34771661, 2021). "Besides driving proinflammatory immune responses via STING and NF-κB, the DDR promotes tumor cells to express ligands for the activating NK cell receptors NKG2D (Killer cell lectin-like receptor subfamily K, member 1) and DNAM-1 (DNAX Accessory Molecule-1) via ATM and ATR signaling." (PMID 34638302, 2021). "Furthermore, neither Rosa26_Alkal2;Th-MYCN nor Alk-F1178S;Th-MYCN NB mouse tumours harbour genetic abnormalities syntenic to human 11q deletions that would support increased sensitivity to ATRi treatment as a result of decreased ATM or other DDR response component activity." (PMID 34819497, 2021).
tumor (continued). "Given the number of mutations and the nature of the mutations found, including at least one tumor suppressor gene, TP73, and several genes that may be associated with other types of malignancy (ATM, CDH5, MAGED1), WDPM clearly appears to be a functionally benign neoplasm and not a reactive process." (PMID 32545767, 2020). "In the absence of androgen, the Tyr267 phosphorylation of AR can promote ATM transcription, and studies have shown that increased expression of ATM protein and upregulation of genes related to maintenance of gene integrity may prevent the death of CPRC tumor cells." (PMID 31772931, 2019). "Importantly, according to the wide range of functions exerted by ATM kinase activity, ATM inhibition may be useful to sensitize tumor cells also to other therapeutic approaches that do not target the DDR." (PMID 24681585, 2014). "Evaluation of three other tumor-suppressor gene promoters revealed no significant changes, although methylation status was reduced by 11% in RASSF1 and ATM genes after higher aronia dosing." (PMID 39435289, 2024). "Unlike genetic manipulation in tumor cells, however, systemic therapies like AZD1390 also inhibit ATM in the tumor immune microenvironment." (PMID 38376927, 2024). "B7-H3 is overexpressed in tumours with defective DNA repair (DDR) gene (ATM, BRCA1/2) alterations compared to tumours without DDR gene alteration." (PMID 36114082, 2023). "However, a recent analysis of tumor biopsies from patients treated with olaparib on the TOPARP-B clinical trial found that loss of ATM protein expression by immunohistochemistry (IHC) was associated with longer PFS and overall survival than was observed in cases without ATM loss by IHC16,17." (PMID 35768576, 2022). "But the molecular mechanism by which ATM mediates chemo-resistance, EMT and tumor metastasis is not fully understood." (PMID 30961670, 2019). "Although previous studies documented that FdUrd activates the ATM- and ATR-dependent checkpoints, these studies did not compare the effects of ATM and ATR depletions on the survival of tumor cells exposed to both agents." (PMID 22194930, 2011). "Additionally, although the monotherapy effect of KU60019 was not as significant as ATM gene deletion, it enhanced the therapeutic effects of combined immunotherapy and radiotherapy in the CT26 tumor model." (PMID 39033176, 2024). "Similar to the analysis of ATM, we did not observe an impact of DNA-PKcs expression levels on patient OS or RFS, neither in HPV-negative HNSCC, p16-positive OPSCC and independent of treatment and tumor sublocalisation (not shown)." (PMID 39478631, 2024). "ATM depletion did not affect the growth of tumor cells in vitro, as demonstrated by crystal violet staining and CCK-8 assay, suggesting that there were no cell-intrinsic growth defects in ATM KD cells." (PMID 36778120, 2023). "Overall, across all 11 PDXs regardless of the nature of the ATM alteration, AZD6738, AZD7648, and olaparib monotherapy treatments (at any dose level) all achieved a minimum best response of 50% tumour growth inhibition (TGI) in 4 out 11 models (36%) albeit the responses were not in the same models." (PMID 37627223, 2023). "A reduction in autophagy, by the deletion of one allele of the Beclin1 gene, reverted some of the mitochondrial phenotypes and significantly delayed tumor suppression without affecting the DDR, providing evidence that autophagy promotes tumorigenesis in the absence of ATM." (PMID 23532176, 2013). "Consistently, absence of ATM, CHK2 or 53BP1 can mean escape of embryonic lethality in BRCA1 knockout mice and suppression of accelerated aging albeit at the expense of entering a tumor-prone state." (PMID 23354477, 2013).
tumor (continued). "Our data supports the hypothesis that in MF cells, uniquely, higher GZ17-6.02 concentrations regulate novel mechanisms, independent of the ATM-AMPK-mTORC1/ULK1 pathway we have previously observed using GZ17-6.02 in solid tumor cells, to further enhance macroautophagy and MF tumor cell killing." (PMID 38329728, 2024). "Although the retention of the 11q and ATM genotypes and lack of latently EBV-infected healthy B cells indicate that the majority of B cells in these xenografts were tumour-derived, it is plausible that in similarity to T cells, B-cell chimerism could occur in the cord blood model." (PMID 26398941, 2015).
infection (136 papers, 2008 to 2025). The state of being infected such as from the introduction of a foreign agent such as serum, vaccine, antigenic substance or organism. "Whilst data demonstrates the efficacy of FDC and CZA+ATM against infections caused by CPOs, cost considerations must be taken into account when evaluating their clinical utility." (PMID 40261267, 2025). "In Poland, 23 patients with infections caused by NDM-producing K. pneumoniae achieved bacterial eradication following treatment with CZA+ATM, though four died due to non-infection-related causes." (PMID 40261267, 2025). "al. also the combination MER/VABORBACTAM + ATM was effective for the treatment of infection caused by GNB MBLs strains." (PMID 41375718, 2025). "Previously, we reported that ATM inhibition during a BKPyV-infection caused cells to complete S phase and enter mitosis rather than re-replicating." (PMID 39636788, 2024). "The loss of ATM protein leads to the blocked V(D)J recombination process, which inhibits the development of the immune system and makes patients vulnerable to infection." (PMID 35586824, 2022). "In the same manner as phosphorylated H2AX, phosphorylated ATM was induced within 30 min post infection, and the inhibition of ATM activity caused a reduction of LANA expression, while knockdown of Chk1 and Chk2 did not affect LANA expression." (PMID 33425783, 2020). "It is consistent with the parvovirus life cycle, which depends upon the induction of a cell cycle arrest, is susceptible to ATM inhibitors, and which continually induces cellular DNA damage during its infection." (PMID 30028293, 2018). "In this report, infection by JCV or transient transfection with a T-Ag expression plasmid resulted in activation of ATM and ATR causing cells to accumulate in the G2 phase of the cell cycle." (PMID 28202068, 2017). "Loss of both ATM and DNA-PKcs (Scid:AtmC/C:Lyz2Cre/+) leads to a significant reduction in IL-1β production in response to infection of BMDMs with L. monocytogenes." (PMID 28362262, 2017). "Clearly the two ATM− cell lines tested here have adapted in different ways, since they differed in virus production at late times in infection despite having identical mutations in the ATM gene." (PMID 26817608, 2016). "Human cytomegalovirus (HCMV) infection induces a DDR centered on the activation of ataxia telangiectasia mutated (ATM) protein kinase." (PMID 21589897, 2011). "It is worthy to underline that double carbapenem therapy may offer similar clinical outcomes as ATM + CAZ-AVI for patients with infection caused by K. pneumoniae resistant to all available β-lactam/β-lactamase inhibitors." (PMID 41375718, 2025). "For the rhesus macaque monkey polyomavirus SV40, infection of permissive CV1 or BSC40 monkey cells causes activation of ATM signaling, H2AX phosphorylation and Mre11-Rad50-Nbs1 assembly with T-antigen together with other DDR-signaling proteins in viral replication foci." (PMID 28202068, 2017). "Therefore, ATM is responsible for the infection-associated DDR prior to the formation of mature RCs." (PMID 21589897, 2011). "One reason for infection-associated ATM activation may be to utilize the consequential stimulation of cellular DNA repair and recombination enzymes to benefit viral replication." (PMID 21589897, 2011). "eGFP-tagged recombinant SVV (rSVV-eGFP) infection-induced γH2AX foci accumulation was accompanied by co-localization with p-ATM in nuclear foci, while γH2AX foci accumulation was not accompanied by co-localizing 53BP1 foci in rSVV-eGFP infected BHK-21 cells." (PMID 40008889, 2025). "To date, the combination of ceftazidime-avibactam with aztreonam (CAZ-AVI + ATM) has been the commonly preferred treatment for infections with MBLs strains." (PMID 41375718, 2025). "Altogether, these findings confirm that T. gondii RH-infected host cells suffer from infection-driven DNA double-strand breaks and elicit a DNA damage response by activating the S-/G2-phase-related ATM-dependent branch of the HR pathway." (PMID 38524184, 2024).